AKR1B10 (aldo-keto reductase family 1 member B10)
Diseases named in the same sentence as AKR1B10 in open-access papers (continued):
Sharing a sentence is not in itself a finding about the gene and the disease.
AKR1B10 also shares sentences with these, for which no sentence is quoted: atopic dermatitis (4 papers); adenocarcinoma (3); type 2 diabetes mellitus (3); alcoholic hepatitis (2); chronic hepatitis (2); ductal carcinoma in situ (2); esophageal cancer (2); gastric adenocarcinoma (2); Insulin resistance (2); kidney cancer (2); laryngeal squamous cell carcinoma (2); viral infection (2); acute leukemia (1); acute liver failure (1); acute respiratory distress syndrome (1); adenoid cystic carcinoma (1); allergic disease (1); asthma (1); basal cell carcinoma (1); benign prostatic hyperplasia (1); bile duct cancer (1); Chronic colitis (1); chronic hepatitis B (1); chronic kidney disease (1); colorectal (1); colorectal adenoma (1); endometriosis (1); esophageal squamous cell carcinoma (1); fibrosis (1); gastrointestinal carcinoma (1).
A further 19 diseases each share a sentence with AKR1B10 in 1 paper.